EGFR (epidermal growth factor receptor)
Diseases named in the same sentence as EGFR in open-access papers (continued):
Sharing a sentence is not in itself a finding about the gene and the disease.
tumor (continued). "Further, a statistically significant association was observed between tumour size, stage, host response, tumour differentiation, and EGFR expression with lymph node metastasis (p < 0.05)." (PMID 33123565, 2020). "Currently, the Greek National Health System provides access to EGFR mutation testing for patients diagnosed with NSCLC but only from tumor tissue specimens." (PMID 32599934, 2020). "EGFR mutations were detected in tumor tissue and plasma of 65 (52.0%) and 50 (40.0%) cases, respectively (P = 0.028)." (PMID 32746896, 2020). "These enriched functions in tumors of Group B reflected the impact of genetic variation, which included TERT promoter mutation, EGFR amplification, and combined 7 + /10−, on the tumor with similar histologic features." (PMID 33195221, 2020). "We established a xenograft tumor model with nude mouse using DLD1 cells with WT or mutated KRAS to examine the effects of AMPK activation on KRAS mutation-mediated anti-EGFR antibody resistance." (PMID 32703218, 2020). "Here, mice with conditional mutant EGFR and Pten loss exhibited accelerated spinal tumor development, confirming a key role of Pten in spinal gliomagenesis." (PMID 32727536, 2020). "In their analyses, low SUVmax of primary tumor, lymph node, and distant metastasis were associated with EGFR mutations." (PMID 32742498, 2020). "For instance, it is possible that the EGFR-mutated phenotype results in a unique tumor physiology that results in higher rates of microscopic foci of disease, even at a clinically low stage." (PMID 32523650, 2020). "In this study, we evaluated the actual sensitivity of the cobas test with small biopsies performed as a usual clinical practice to identify the importance of tumour cellularity in the specimen slice when identifying EGFR mutations." (PMID 32028905, 2020). "Targeting different tumor-associated antigens (EpCAM/EGFR) on the tumor cell is expected to support the combinatorial approach by avoiding competition between the fusion proteins mediating the first and the costimulatory signal, respectively." (PMID 32504247, 2020). "EGFR mutations were detected in 65 (52.0%) tumor tissue and 50 (40.0%) matched plasma samples (P = 0.028)." (PMID 32746896, 2020). "Meanwhile, due to the difficulty in obtaining sufficient amounts of tumor tissue and repeat tumor biopsy, there is a growing trend of testing EGFR mutations using liquid biopsy." (PMID 32224854, 2020). "When we compared the number of copies of the EGFR mutations (L858R and 19del) found in 13 BW-derived EV-DNA samples and the corresponding tumor size measured from CT scan images, there was weak positive correlation." (PMID 33007940, 2020). "Factors associated with better OS were age (<60 vs ≥60, 29.9 vs 22.1; P = .048), ECOG PS (<2 vs ≥2; 28.9 vs 19.4 months; P = .001), tumor differentiation grade (27.5 vs 17.7; P = .029), and EGFR (+) mutation status (39.8 vs 20.9 months; P = .001)." (PMID 32043750, 2020). "Despite the association with a high PD-L1 expression in a small cohort of resected NSCLC specimens, the presence of activating EGFR mutations is associated with low expression of PD-L1 on tumor cells, as well as a poor outcome to ICIs." (PMID 33114576, 2020). "Predictive model including 9 factors (smoking, pathology, location, EGFR mutation, age, tumor diameter, clinical N stage, consolidation chemotherapy and radiation dose) was finally built with the best performance." (PMID 32070383, 2020). "In BC, approximately over 50% of tumour specimens presented higher EGFR expression and were associated with recurrent, high-grade, and high-stage patients, as well as having a worse prognosis." (PMID 32872665, 2020). "Next‐generation sequencing (NGS) and digital polymerase chain reaction (PCR) based platforms have been used to detect EGFR mutations in plasma circulating tumor DNA (ctDNA) with high accuracy." (PMID 31991049, 2020).
tumor (continued). "Studies have shown that although the positive rate of PD‐L1 in tumor specimens with EGFR/ALK mutations is high, the ratio of high levels of CD8+TILs is very low, which limits the antitumor effect of anti‐PD‐1/PD‐L1 monoclonal antibody." (PMID 32875727, 2020). "As far as we know, the parallelism between the dynamics of EGFR mutation status and radiomic features is potentially dependent on the progressive enrichment of tumor tissue by treatment-resistant clones." (PMID 33489892, 2020). "For instance, using CF-LAMP, a clinician can easily determine the suitability of the patient for TKI therapy by checking the status of sensitizing EGFR mutations in tumor-derived DNA from peripheral blood." (PMID 33067539, 2020). "Results shown that the optimal model incorporated nine features including smoking, pathology, location, EGFR mutation status, age, tumor diameter, clinical N stage, consolidation chemotherapy and radiation dose." (PMID 32070383, 2020). "The tumor cell-autonomous mechanisms include mutations in the EGFR or downstream-related genes, as well as activation of compensatory loops such as human epidermal growth factor receptors 2 and 3 or AXL (HER2 and HER3, respectively)." (PMID 32028632, 2020). "The CTCs can accurately detect EGFR gene mutations and can solve the problem of obtaining tumor tissue in clinical settings." (PMID 32856417, 2020). "A total of 901/1368 (66%) biopsies had more than a 10% tumor cell content, allowing for the assessment of EGFR mutations using the Idylla assay." (PMID 32294880, 2020). "CTC detection can accurately identify mutations in the EGFR gene and improve the ability to obtain tumor tissue in clinical practice." (PMID 32856417, 2020). "Some SEs exhibited subtype-specific enrichment; for example, RTK II tumours have an intronic SE in EGFR that is associated with higher H3K27ac signal and EGFR expression in this subtype." (PMID 33339831, 2020). "Association between infiltration of CD68+ macrophages and EGFR-status was demonstrated in study of 105 surgically resected tumor samples (50 EGFR mutated and 55 EGFR wild-type)." (PMID 33194645, 2020). "The activating EGFR mutation L858R was identified in tumor tissue of two patients with either ERBB2 G660C (P22) or G660D (P26)." (PMID 32478891, 2020). "This tumor suppressor inactivation is accompanied by decreased EGFR expression, despite the persistence of the EGFR activating mutation." (PMID 35582610, 2020). "Further, the precise histology including patterns of invasive adenocarcinoma were not available preventing us from investigating the association between tumour histology and EGFR mutation detection with cobas." (PMID 32028905, 2020). "EGFR overexpression (EGFRover) was tracked in 1039 primary tumours, circulating tumour cells from 39 d’Amico high-risk patients and metastatic samples from 21 castration-resistant PCa cases." (PMID 32901137, 2020). "Here, we report a case of locally advanced SqCC harboring EGFR exon 19Del/T790M mutation with a pathological complete tumor response after osimertinib treatment." (PMID 32667739, 2020). "A limited number of studies conducted with quantitative of semi-quantitative mutation detection methods have suggested a correlation between the amount of the sensitizing EGFR mutant allele (sEGFRma) in plasma and tumor burden." (PMID 32215186, 2020). "Our results support use of the two tests interchangeably for EGFR activating mutation diagnosis in tumor samples." (PMID 32224854, 2020). "Current molecular testing for identifying EGFR mutation status is mainly based on tumor tissue from biopsies and surgical resection." (PMID 33134170, 2020). "Firstly, they identified an increase of CD8+ T cells in EGFR wild-type patient tumours compared to tumours harbouring the EGFR-19 del mutation." (PMID 33143170, 2020). "The efficacy of third-generation EGFR TKI osimertinib on choroidal metastasis was reported once in an NSCLC patient with T790M EGFR tumor mutation." (PMID 33272243, 2020).
tumor (continued). "For example, using 80 small routine samples from routine biopsies and cytology, De Biase compared NGS with Sanger sequencing, and demonstrated that NGS improved detection of EGFR mutations, particularly in samples with low tumor cell content." (PMID 32928143, 2020). "The association of smoking with the low EGFR frequency in tumor tissue and plasma samples of NSCLC has been shown in many studies." (PMID 32746896, 2020). "In the combination therapy group, only one of the seven patients with tumor EGFR mutations had progressive disease, and the other six patients had stable disease." (PMID 33102221, 2020). "The increased rate of metastatic recurrence in EGFR-mutated disease found in this study suggests both distinct tumor physiology as well as a need for earlier use of tumor molecular genetics." (PMID 32523650, 2020). "On the other hand, low EGFR expression in CRC cells is correlated clinically with low tumor metastasis risk and better survival." (PMID 32756527, 2020). "In this study, we used the scorpion ARMS method to detect EGFR mutations in plasma samples and showed a high agreement with the tumor tissues together with a moderate sensitivity and excellent specificity." (PMID 32746896, 2020). "This was also associated with enhanced EGFR expression; thereby conferring tumor-propagating cells a growth signal for their survival in the tumor microenvironment." (PMID 30517668, 2020). "At the end of the imaging study, we sectioned the tumors and stained the EGFR-positive tumor cells, tumor-associated fibroblasts, and cetuximab to evaluate the residual antibodies and their spatial distributions." (PMID 33028895, 2020). "At the time of clinical diagnosis, the detection of EGFR mutations in tumor tissue or ctDNA, when tissue is unavailable, is mandatory for the selection of patients." (PMID 32215186, 2020). "By functionalizing an Au coated slide with antibodies against tumor-associated proteins (EGFR and PD-L1), absolute specificity was conquered, separating cancer exosomes from the others." (PMID 32214017, 2020). "For EGFR mutations, the sensitivity of the assay increased with higher numbers of detected CTCs with concordance between EGFR mutation status in the tumor and CTC samples." (PMID 32992872, 2020). "Although these studies showed that PET was able to identify EGFR mutation positive tumours, the short half-life of 11C restricts the application of [11C] erlotinib in widespread clinical practice." (PMID 32804306, 2020). "The somatic alteration EGFR exon 2–28 duplication (existed in both preimmunotherapy and postimmunotherapy tumor tissues) was thought to be associated with HPD, which was never reported before." (PMID 32581041, 2020). "But EGFR is an oncogene; the abnormality of its related pathways is closely associated with tumor development, invasion, metastasis and drug resistance 1-4, 16-19." (PMID 32127953, 2020). "The EGFR copy number gain in tumor cells is associated with increased mutant allele transcription and gene activity." (PMID 32631368, 2020). "It shows that mutations such as EGFR mutation, in addition to the tumor cells’ proliferation can affect angiogenesis induction." (PMID 33112545, 2020). "In this retrospective study, we included 21 NSCLC patients (13 males, 58 ± 12 years old; 8 females, 63 ± 11 years old) presenting EGFR mutations in their tumor samples." (PMID 30809319, 2019). "Some significative mutations were related to volumetric features: EGFR mutations displayed a significantly higher necrosis/contrast enhancing ratio and a significantly lower contrast-enhancing/tumor bulk ratio." (PMID 31795520, 2019).
tumor (continued). "Noteworthy, in one AC sample (N34, EGFR-mutated-positive), we observed that these phospholipids had a distinct distribution in separate regions of the same tumor tissue." (PMID 31555581, 2019). "EGFR is amplified or mutated which leads to tumor cell invasion and tumor‐related angiogenesis via the aberrant activation of downstream signaling networks." (PMID 31508283, 2019). "These EGFR-targeted tyrosine kinase inhibitors (TKIs) such as erlotinib, gefitinib, and afatinib have shown improved tumor response and progression-free survival outcome in EGFR-mutated NSCLC compared with cytotoxic chemotherapies." (PMID 31815659, 2019). "Currently, the assessments for EGFR mutational status are based on biopsies of tumor tissue or surgical resection acquisition." (PMID 31681597, 2019). "Preclinical studies indicate that EGFR mutations mediate tumor immune escape through the PD-1/PD-L1 pathway and that EGFR-TKIs downregulate PD-L1 expression." (PMID 31526368, 2019). "Most of the cases with inherited EGFR mutation in our investigation had concurrent activating mutations in their tumours." (PMID 31703574, 2019). "The third mouse generation of YHIM-1009 (EGFR 19del mutation/ PIK3CA E542K) tumor model, an acquired-gefitinib resistant tumor, was used for drug efficacy testing." (PMID 31043587, 2019). "Yet, the mechanisms underlying the tumor-promoting effects of EGFR antibodies observed in patients with RAS mutant tumors remain largely unclear." (PMID 32039027, 2019). "Elevated expression levels of EGFR are associated with prognosis and clinical outcomes of patients in a variety of tumor types." (PMID 31438847, 2019). "According to gene mutation types, tumor driver gene-derived inhibitors (including EGFR inhibitor, ROS1 inhibitor, and ALK inhibitor) have been screened and used for stratifying treatments in NSCLC patients." (PMID 31572680, 2019). "By drug screening, we found that ABT-263 can significantly enhance the antitumor activities of apigenin in tumor cells harbouring an activating EGFR mutation and AZD9291-resistant H1975 cells." (PMID 31367332, 2019). "The aim of this study was to evaluate a fluorescent-labelled erlotinib based theranostic agent for the molecular imaging of mutated EGFR tumours in vitro and ex vivo using a mice xenograft model and fibred confocal fluorescence microscopy (FCFM)." (PMID 30612556, 2019). "Tumor EGFR mutation status is an important variable in the selection of regimens for patients with advanced NSCLC." (PMID 31419239, 2019). "Our study has very high (94.7%) concordance between tumor tissue DNA and cfDNA for EGFR mutation detection (Exons 18, 19, and 21 mutations)." (PMID 31870098, 2019). "For reason given above, it is urgent to seek a new source of tumor DNA for detection of EGFR mutation." (PMID 31608233, 2019). "Out of 20 patients who had detectable activating EGFR mutation in their tumor tissue, 18 patients exhibited mutation in their cfDNA from plasma." (PMID 31870098, 2019). "Genes implicated in the EGFR subtype were examined for overall survival across the LUAD tumor cohort (n = 230) using the Kaplan-Meier tool in cBioPortal." (PMID 31857847, 2019). "As first-line treatment, these TKI improve progression-free survival in patients with tumours harbouring EGFR sensitive mutations." (PMID 30612556, 2019). "CB-treated MCF-7 cells exhibited 80–90% expression levels of EpCAM and EGFR proteins on their surface, while CB-induced EVs also overexpressed these tumor-associated genes." (PMID 31728677, 2019). "In the 51 patients with EGFR mutation detected in the tumor tissue, 33 (65%) patients had concordant EGFR mutation test results in liquid biopsy, while 18 (35%) patients had discordant results." (PMID 31652678, 2019). "We obtained plasma samples from 21 advanced NSCLC patients with known EGFR tumor mutations, before and during therapy with EGFR-TKIs and/or chemotherapy." (PMID 30809319, 2019).
tumor (continued). "Clinical characteristics, type of tumor, EGFR mutation status, and treatment response to first-line EGFR-TKI therapy and efficacy of TTS1, were collected." (PMID 31579626, 2019). "This is at the first glance surprising because human cSCC tumors highly express both EGFR and the proliferation marker Ki67 at the tumor invasion front and EGFR signaling has been implicated in cSCC proliferation." (PMID 31867038, 2019). "We demonstrate the usefulness of the model by quantifying the impact of mutational alterations in the EGFR/ERK pathway on the growth rate of in silico tumours." (PMID 31016574, 2019). "EGFR mutations can be detected by analyzing circulating tumor DNA (ctDNA) in both plasma and cerebrospinal fluid (CSF), which provides an alternative to tumor biopsies for further study." (PMID 31368671, 2019). "EGF/EGFR‐induced signaling is associated with organ morphogenesis, maintenance, and repair, as well as tumor invasion and metastasis." (PMID 31026363, 2019). "As we were working on EGFR and this gene was linked to chemotherapy-resistance and tumor malignancy, protein expression of this factor was further examined in these cells with both Western blot technology and ICC." (PMID 31998647, 2019). "Because of the heterogeneous nature of intra-tumor development, it was necessary to developed highly selective and sensitive methods to detect the low-abundance EGFR mutations present in various clinically available samples, such as FFPE tissue sections." (PMID 31164704, 2019). "The analysis of cfDNA detected the same EGFR activating mutation reported in the tumor tissue in 20/29 patients, with a sensitivity of 69%." (PMID 31557965, 2019). "In this study, the EGFR mutation rate detected in tumor tissues, cell blocks, and exosomes were 32.26, 51.52, and 46.15%, respectively, with the mutation types focusing on exon 19 Del and exon 21 L858R, which was in accordance with previous study." (PMID 31608233, 2019). "Recently, it was also demonstrated that TKI-induced EGFR dimerization is a critical mechanism for facilitating acquired resistance in cells harboring EGFR T790M mutation and that targeted reduction of EGFR resulted in tumor regression." (PMID 31121829, 2019). "Studies have shown that one of the root causes of tumor resistance is the occurrence of a second site mutation in the EGFR gene." (PMID 31367332, 2019). "In NSCLC patients, ctDNA sequencing of tumor plasma was reported to be as useful as tumor tissue genotyping to follow the appearance of specific mutations such as EGFR(T790M) mutations at the time of tumor progression." (PMID 31134126, 2019). "In this study, for the first time, circulating miR-504 levels in plasma from NSCLC patients were measured and compared to previously published results on differential miR-504 expression in tumour tissue relative to the EGFR mutation status of NSCLC patients." (PMID 30953094, 2019). "In these studies, rociletinib was associated with tumor responses and sustained disease control among patients with heavily pretreated EGFR-mutated NSCLC (NCT01526928)." (PMID 30975211, 2019). "And patients who were detected as wild type in tumor tissues or cell blocks but EGFR mutation in exosomes turned up as PR or SD." (PMID 31608233, 2019). "In our study, the presence of EGFR mutations in plasma ctDNA was also associated with a larger tumor size." (PMID 31185703, 2019). "Whereas reports on the frequency of genetic alterations of NF1 in CRC show varying results, a recent study associated mutant NF1 with tumor progression and anti-EGFR therapy resistance." (PMID 30858928, 2019).